ALB (albumin)
Diseases named in the same sentence as ALB in open-access papers (continued):
Sharing a sentence is not in itself a finding about the gene and the disease.
diabetes (continued). "The results showed that systolic blood pressure, diastolic blood pressure, course of diabetes, FBG, 2hPBG and urinary albumin were independent risk factors for T2DM complicated with PDR (Table-III)." (PMID 38545017, 2024). "During GA level monitoring, the ratio of GA to total human serum albumin (HSA) is referred for diagnosing diabetes." (PMID 39008069, 2024). "Stratification analyses stratified by body mass index (BMI), sex, hypertension, drinking, diabetes, education level and albumin-creatinine-ratio (ACR) revealed that the DII score was also associated with the risk of hyperuricemia (P<0.05)." (PMID 38974578, 2024). "Albumin is the most abundant protein in plasma whose glycation is well-studied in diabetes mellitus." (PMID 38741158, 2024). "Background/Objectives: Glycated albumin (GA) serves as a biomarker for short-term glycemic control (2–3 weeks), playing a role in diabetes management." (PMID 39767558, 2024). "Univariable analysis revealed associations between BMI, age, sex, history of hypertension, diabetes mellitus, dyslipidemia, serum albumin, fasting glucose, and total cholesterol with incident osteoporosis." (PMID 38605101, 2024). "A previous meta-analysis showed that serum total and albumin-adjusted calcium were positively correlated with incident diabetes, consistent with the findings of a retrospective cohort study." (PMID 38505748, 2024). "This decreased risk persisted even after adjustment for creatinine, albumin, MIS, LVMI, PVD, diabetes and age." (PMID 39064068, 2024). "LPD patients were older, predominantly female, had a higher BMI, smoked more, had worse eGFR, lower serum albumin, and higher rates of hypertension, diabetes, anemia, and hyperlipidemia (P < 0.05)." (PMID 39004744, 2024). "Studies have demonstrated that low albumin levels, age over 65, diabetes, employment status, Kt/V ≥ 1.8, ClCr ≥ 50 L/week/1.73 m2 are all associated with worse survival outcomes." (PMID 38493084, 2024). "Age, history of diabetes, iPTH, hemoglobin, calcium and serum albumin levels predicted medication needs." (PMID 38378456, 2024). "DN in people with diabetes is detected early by urine microalbumin, which is characterized by quantitative estimation of urine albumin of 30-300 mg/ day or as urine albumin creatinine ratio (UACR) between 30 and 300 mg/gm." (PMID 39131026, 2024). "Univariate analysis indicated that age, diabetes status, MIS, age-adjusted CCI, hs-CRP, and albumin were significantly associated with the risk of sarcopenia in both overweight and non-overweight participants." (PMID 38351264, 2024). "Diabetes kidney disease, commonly referred to as diabetic nephropathy (DN) is marked by diabetes‐related glomerular lesions, pathological levels of urine albumin excretion, and a decrease in the rate of glomerular filtration in diabetics." (PMID 38726403, 2024). "Model 3 further includes education, blood pressure, BMI, cholesterol, uric acid, serum albumin, diabetes, CVD, and stroke." (PMID 39355620, 2024). "These encompassed daily living activity capability, NIHSS score, diabetes, BMI, grip strength, serum albumin, and depression." (PMID 38761298, 2024). "After comparing and contrasting the renal parameters of the male and female participants, we discovered that male diabetics had higher serum urea, creatinine, urine albumin, urine creatinine, urine ACR, and normalized urine MMP-7 levels than female diabetics." (PMID 39246865, 2024). "The aim of this study is to explore the association between red blood cell distribution width–to–albumin ratio (RAR) and the risk of peripheral artery disease (PAD) in patients with diabetes." (PMID 38405142, 2024). "A previous study revealed a significant increase in albumin levels among individuals suffering from both types of diabetes." (PMID 39014510, 2024).
diabetes (continued). "Furthermore, the results from a cohort study showed that decreased urinary albumin excretion was related to the decreased risk of cardiovascular events among patients with diabetes, emphasizing the significance of reducing the incidence of proteinuria in diabetes." (PMID 38459493, 2024). "In multivariate Cox proportional analysis, we found that inflammation was the only factor significantly associated with high mortality when we adjusted for age, vintage, diabetes mellitus, iPTH, Osteoprotegerin, Albumin, and hs-CRP." (PMID 39335504, 2024). "The nomogram amalgamates diverse autonomous risk elements, encompassing energy intake, age, anemia, serum albumin, BMI, eGFR, and diabetes, discerned through weighted multivariate Cox regression scrutiny." (PMID 39004744, 2024). "In contrast, body temperature, GCS score, urine volume, calcium, bicarbonate, total protein, albumin levels, and a history of diabetes were negatively correlated with mortality (all P < 0.001)." (PMID 39659626, 2024). "Combinations of age, diabetes status and iPTH, calcium, hemoglobin and serum albumin levels predicted the use of ESA, iron, phosphate binder or VDRA, with C-statistics of 0.70, 0.64, 0.73 and 0.63 in derivation cohorts respectively." (PMID 38378456, 2024). "These scores are calculated by various combinations of factors, including age, sex, BMI, AST and ALT levels, platelet count, albumin level, and the presence of diabetes mellitus (DM)." (PMID 39199546, 2024). "Among the three groups, there were also significant differences regarding ethnicity, type of diabetes albumin, international normalized ratio (INR), serum creatinine, and serum sodium levels." (PMID 38921280, 2024). "The diagnosis of DKD is based on sustained elevation of urinary albumin excretion (urine albumin to creatinine ratio >30 mg/g) and/or a reduction in estimated glomerular filtration rate (eGFR) to <60 mL/min/1.73 m2 in a patient with diabetes." (PMID 38675379, 2024). "Glycated hemoglobin (HbA1c) and glycated albumin (GA) are vital markers for assessing glucose control in diabetes." (PMID 38497074, 2024). "Quantifying glycated albumin (GA) levels in the blood is crucial for diagnosing diabetes because they strongly correlate with blood glucose concentration." (PMID 39008069, 2024). "Glycated albumin is less likely to be affected by confounding factors, although it can also be impacted by low albumin levels, and data suggest it can predict mortality and hospitalisation rates in people with diabetes mellitus and ESKD." (PMID 39112642, 2024). "For patients with T2DM, blood pressure, course of diabetes, FBG, 2hPBG and urinary albumin are independent risk factors for PDR, and increased systolic blood pressure, course of diabetes, HbA1c level and urinary albumin level will increase CMT." (PMID 38545017, 2024). "The measurement of albumin levels in serum and urine is an important aspect of clinical diagnostics, particularly in the context of chronic diseases such as diabetes." (PMID 39125606, 2024). "In these patients, age, the presence of diabetes, serum calcium and phosphorus levels, HD vintage, CCI scores, UFV, the use of clopidogrel, female sex, BMI, Kt/Vurea, and levels of hemoglobin, albumin, and creatinine played a role in all-cause mortality." (PMID 38673676, 2024). "The final study population was 2/3 male, with an average age of 58 years, a diabetes duration of 8.5 years, a mean HbA1c of 52 mmol/mol, and an average urine albumin/creatinine ratio in the micro-albuminuric range." (PMID 38184612, 2024). "Chronic diseases such as diabetes and liver disease can lead to a decrease in albumin synthesis or an increase in degradation, resulting in a decrease in plasma albumin concentration." (PMID 38584822, 2024).
diabetes (continued). "Sex, age, hypertension, diabetes, hemoglobin, serum albumin, serum creatinine, eGFR, urinary protein,anti-PLA2R antibody levels and domains specific antibody levels except for PLA2R-CTLD678 IgG4 were comparable between the two groups (P> 0.05)." (PMID 38718066, 2024). "American Diabetes Association (ADA) and the National Kidney Foundation (NKF) guidelines define microalbuminuria by an albumin-to-creatinine ratio (ACR) of 3.39-33.9 mg/mmol (30-300 mg/g)." (PMID 39759667, 2024). "Diabetic nephropathy (DN) is an illness marked by a steady rise in urine albumin and a decrease in glomerular filtration rate, making it a serious diabetes consequence." (PMID 39280507, 2024). "Based on univariate analysis, the FI, preoperative MMSE score, hyperlipidemia, diabetes mellitus, cerebrovascular disease, hemoglobin and albumin levels, operation time and CPB time were found as significant risk factors for POD." (PMID 39171326, 2024). "Recent studies indicate the relevance of early glycated albumin in diabetes pathology, showing its specific binding to the RAGE ectodomain." (PMID 39766199, 2024). "Studies have shown that urine albumin in people with diabetes is altered due to the glycation and attachment of fatty acids and its partial hydrolysis in the tubular lumen." (PMID 39131026, 2024). "Patients with DKD were defined as those with diabetes who had a urinary albumin-to-creatinine ratio ≥ 30 mg/g and/or an estimated glomerular filtration rate < 60 mL/min/1.73 m2." (PMID 39731593, 2024). "In the multivariable analysis, the subject age, gender, smoking status, alcohol consumption, diabetes status, eGFR, serum albumin level, uric acid level, blood urea nitrogen level, and VPA were identified as independent factors for all-cause mortality." (PMID 39482632, 2024). "The total point count of each patient increased with age, as did calcification, an increase in LDL-C, low albumin, comorbid diabetes, and CHD/stroke." (PMID 39026232, 2024). "Glycated human serum albumin (HSA) increases in diabetics as a consequence of elevated blood glucose levels and glycating metabolites like methylglyoxal (MGO)." (PMID 39766199, 2024). "Patients in the low-AFR group were older, had higher rates of hypertension and diabetes, higher levels of blood urea nitrogen, total protein, urinary microalbumin, globulin, and fibrinogen, but lower levels of albumin and total urine output over 24 h." (PMID 39281816, 2024). "There were differences between the Na quartiles in terms of body weight, diabetes, systolic blood pressure, interdialytic weight gain, total ultrafiltration, serum glucose, albumin, and creatinine, vascular access, and hemolysis type." (PMID 39525164, 2024). "It was formerly reported that among adult T1DM patients, NLR positively correlated with creatinine and HbA1c levels, and negatively correlated with albumin level after adjusting for age and duration of diabetes." (PMID 38989212, 2024). "Elevated HbA1c, fructosamine, glycated albumin, and FBG were associated with mortality risk in older adults with diabetes." (PMID 38769875, 2024). "The review covers the detection of several key diabetes biomarkers, such as glucose, glycated hemoglobin (HbA1c), glycated human serum albumin (GHSA), insulin, and novel biomarkers." (PMID 39091901, 2024). "In individuals with diabetes, fluctuations in serum albumin are notuncommon either due to incipient or overt nephropathy, and since calcium largely binds to albumin, changes in albumin levels caninfluence total calcium readings." (PMID 38352911, 2024). "Compared to younger patients, older patients have a lower proportion of men, a higher proportion of comorbid diabetes, poorer cardiac function, lower levels of blood albumin, and lower levels of serum phosphorus (p < 0.05)." (PMID 38622550, 2024).
diabetes (continued). "The general condition of diabetes rats was improved after the treatment of Mudan granules, the 24-h urinary protein and urinary albumin to creatinine ratio were reduced, and the renal function and lipid results were modified." (PMID 38357745, 2024). "The model indicators used in this study include preoperative fever, ASA, PT, hsCRP, BUN, diabetes, duration of surgery, ulinastatin, methylprednisolone, ALT, total volume of fluid loss, volume of blood loss, DBILI, albumin, and gender." (PMID 39501984, 2024). "Prospective and epidemiological studies in people with diabetes have shown that development of microalbuminuria, i.e. small quantities of albumin in the urine, is an independent predictor of progressive renal disease." (PMID 38302978, 2024). "Our study indicates that ALB is a significant contributing factor to the development of sepsis in individuals with diabetes and UTI." (PMID 38771840, 2024). "Utilizing a meta-analytical approach, studies published from January 2015 to December 2022 were systematically collected and analyzed through the assessment of factors like body mass index, diabetes, albumin levels, malnutrition, and surgical duration." (PMID 39193402, 2024). "Unfortunately, in Japan, urinary albumin levels are routinely monitored in only approximately 20% of individuals with diabetes." (PMID 39031296, 2024). "The primary aim of this study was to investigate the correlation between diabetic retinopathy (DR) and the HALP score (hemoglobin, albumin, lymphocyte, and platelet) in individuals with diabetes within the United States population." (PMID 38800491, 2024). "Studies have shown that ACAG is a more reliable indicator in clinical settings, especially for patients with conditions like diabetes, where albumin levels can frequently be abnormal." (PMID 39574951, 2024). "Significant differences among these three groups were also found for systolic blood pressure, duration of diabetes, HbA1c, serum hemoglobin, serum albumin, and serum triglyceride." (PMID 39654881, 2024). "The analysis identified high body mass index (BMI), diabetes, preoperative low albumin levels, preoperative malnutrition, and surgical duration exceeding 3 h as significant risk factors for postoperative incision infection in colorectal cancer." (PMID 39193402, 2024). "This relationship persisted after adjustment for subjects’ age, gender, smoking status, alcohol consumption, diabetes status, eGFR, and blood urea nitrogen, uric acid, and serum albumin levels." (PMID 39482632, 2024). "Glomerular injury has been associated with podocyte protein loss, and previous studies have suggested that podocyte damage is associated with increased sCysC, urinary nephrin and urinary albumin in patients with diabetes." (PMID 39524372, 2024). "Correlation analysis demonstrated that CMT was positively correlated with systolic blood pressure, course of diabetes, HbA1c level and urinary albumin level." (PMID 38545017, 2024). "It was shown that evaluation of each pathology such as serum albumin value, diabetes, liver dysfunction, and dehydration was finally important." (PMID 38225984, 2024). "All included patients underwent measurements of serum albumin levels and screening for diabetes-related complications." (PMID 38369636, 2024). "Diabetes, heart failure, renal failure, hemodialysis, and decreased levels of albumin, total lymphocyte, and cholinesterase are closely related to the risk of wound formation, and have been included in a risk model for disease progression." (PMID 39644409, 2024). "Our results showed that the levels of cholesterol, low-density lipoprotein, glycated hemoglobin and glycated albumin, and family history of diabetes and hypertension in MASLD patients with MS were significantly higher than those in patients with MASLD alone." (PMID 39618812, 2024).
diabetes (continued). "In this study, we identified the factors associated with a higher TyG-BMI included advanced age, male sex, history of CVD or diabetes, higher hemoglobin, albumin and LDL-C levels, higher urine output and use of lipid-lowering agents." (PMID 37670344, 2023). "In the unadjusted models, diabetes mellitus, lower serum albumin levels, PPI use, and reduced LVEF (LVEF < 50%) were significantly associated with the first episode of peritonitis." (PMID 38123633, 2023). "Six variables (age, BMI, diabetes mellitus, Child–Pugh class B/C, albumin, and pentosidine) were revealed as significant factors associated with sarcopenia in univariate analysis." (PMID 37780552, 2023). "In the early stages of DKD, urinary albumin excretion and eGFR are usually well-maintained; however, molecular changes induced by diabetes, such as inflammation and oxidative stress, are progressively activated." (PMID 37109492, 2023). "Age, sex, performance status, planned chemotherapy, prior adjuvant chemotherapy, assigned treatment arm, KRAS status, tumor sidedness, plasma albumin, diabetes, BMI, and fasting status." (PMID 37485272, 2023). "After further adjusting for sociodemographic factors, lifestyle factors, hepatitis status, diabetes status and BMI (Model 2–4), the results were attenuated, but the positive associations for ALP, GGT and albumin remained." (PMID 37987396, 2023). "Urinary albumin excretion (UAE) serves as an early diagnostic marker for kidney damage, which is another prevalent complication in diabetes." (PMID 37373782, 2023). "Patients with coronary artery disease (CAD) combined with diabetes have a higher risk of cardiovascular events, and high-sensitivity C-reactive protein (hs-CRP)-to-albumin ratio (CAR) is a novel inflammatory biomarker." (PMID 36747210, 2023). "In this group, older age, larger number of females, higher EuroSCORE II, lower albumin level, and greater incidence of anemia, diabetes mellitus, CKD, CHF (all p < 0.001), and LVEF < 40% (p = 0.017) were observed compared to those in the high mean rScO2 group." (PMID 36615159, 2023). "The prevalence of diabetes, hypertension, smoking status, drinking status, and the level of hemoglobin, albumin, BUN, creatinine, eGFR, calcium and phosphate were significantly different among four groups." (PMID 37560310, 2023). "Multivariate analysis revealed that albumin concentration, diabetes, the laparoscopic approach, and proximal or total gastrectomy were the independent risk factors facilitating AL development." (PMID 37007118, 2023). "This study aims to contribute to understanding the early detection of diabetic nephropathy by assessing the utility of urine albumin estimation among patients with diabetes mellitus." (PMID 37868453, 2023). "The significant independent predictors of CIMT were diabetes duration, BMI (body mass index), albumin/creatinine ratio, and cholesterol." (PMID 37692464, 2023). "The top six risk factors for determining DKD progression to dialysis were hemoglobin, HbA1c, neutrophil percentage, serum albumin, duration of diabetes, and plasma fibrinogen level." (PMID 37308973, 2023). "In diabetes, the level of albumin decreases, the production of oxygen free radicals increases, and the oxidative defence ability decreases and the generation of excessive endogenous neurotoxicity, which causes damage to central nervous system function." (PMID 37576498, 2023). "Aims/Introduction: Diabetic kidney disease (DKD) is defined as diabetes with impaired renal function, elevated urinary albumin excretion, or both." (PMID 37929213, 2023). "In this retrospective study, increased APACHE II score, decreased ALB, diabetes, higher PCT, CAP and extrahepatic lesion involved were identified as independent risk factors for septic shock and ARDS in patients with hvKP infections." (PMID 37626308, 2023).